HNF1B (HNF1 homeobox B)
Diseases named in the same sentence as HNF1B in open-access papers (continued):
Sharing a sentence is not in itself a finding about the gene and the disease.
Hypomagnesemia (18 papers, 2017 to 2026). An abnormally decreased magnesium concentration in the blood. "Hypomagnesemia and hypocalciuria are common in patients with heterozygous HNF1β mutations and deletions." (PMID 35894287, 2022). "Other rare manifestations reported in patients with HNF1B-associated disease include hypomagnesemia and hypocalciuria." (PMID 35474932, 2021). "In another predominantly pediatric cohort, hypomagnesemia was present in only a quarter of patients with HNF1B mutations." (PMID 31517149, 2019). "Importantly, hypomagnesemia was found to be a highly selective parameter for HNF1B mutations, which is in concordance with other studies." (PMID 38196016, 2024). "In the same study, hypomagnesemia had a high relative risk for HNF1B-associated disease." (PMID 38196016, 2024). "Several groups have demonstrated that the presence of hypomagnesemia may be particularly predictive of HNF1β mutations." (PMID 35554666, 2022). "Hypomagnesemia seems to be a good discriminator for HNF1B mutations." (PMID 31066763, 2019). "Mutations in HNF1B and FXYD2 mainly result in hypomagnesemia, hypocalciuria, and basolateral membrane depolarization, leading to increased intracellular chloride levels and inhibiting NCC." (PMID 39408938, 2024). "Alterations in HNF1B often lead to ADTKD-HNF1B, which is characterized by electrolyte imbalances such as hypomagnesemia, hyperparathyroidism, hyperuricemia, and hypocalciuria." (PMID 39408938, 2024). "Here, we confirm that the prevalence of hypomagnesemia increases with age, but noteworthy, we found hypomagnesemia in a substantial proportion of HNF1B patients in younger ages." (PMID 38196016, 2024). "Careful phenotyping of these cohorts has demonstrated that hypomagnesemia, hyperparathyroidism, hyperuricemia, and hypocalciuria are common in patients with HNF1β defects." (PMID 35554666, 2022). "Previously, we reported hypomagnesemia as part of the clinical spectrum, suggesting a role for HNF1B not only in morphological renal development, but also in the maintenance of tubular function." (PMID 31517149, 2019). "Mutations in FXYD2 (G41R), and transcription factors (HNF‐1B and PCBD1) that affect FXYD2 expression are associated with hypomagnesemia with hypermagnesuria." (PMID 30175537, 2018). "We also demonstrated that hypomagnesemia may be an early and common manifestation in individuals with HNF1B and, as such, could serve as a predictor at a young age." (PMID 38196016, 2024). "Hypomagnesemia is often the earliest and primary symptom of HNF1B-related disease." (PMID 35346144, 2022). "Interestingly, at 6 but not 12 months of age, Hnf1b mutant mice exhibited a reduced ability to concentrate urine associated with hypercalciuria but no hypomagnesemia or hyperkalemia was observed." (PMID 35554666, 2022). "Thus, the absence of hypomagnesemia in younger children should not be used as an argument against testing for HNF1B, as the negative predictive value is low." (PMID 31517149, 2019).
autosomal dominant tubulointerstitial kidney disease (17 papers, 2017 to 2025). "The established diagnoses consisted of a variety of nephropathies, including CHARGE syndrome, X-linked and autosomal forms of Alport syndrome, HNF1B-associated disease, Dent’s disease, and autosomal dominant tubulointerstitial kidney disease." (PMID 31921302, 2019). "Aberrant TGFβ1 signaling drives HNF1B-Related Autosomal Dominant Tubulointerstitial Kidney Disease characterized by tubular cysts, renal fibrosis, and progressive decline in kidney function." (PMID 40807208, 2025). "Genes of UMOD, HNF1B, MUC1, REN and SEC61A1 were reported to be associated with autosomal dominant tubulointerstitial kidney disease (ADTKD)." (PMID 33574344, 2021). "Autosomal dominant tubulointerstitial kidney disease–HNF1B is rare and larger cohort studies, ideally based on national or international registries, will be needed to overcome these limitations." (PMID 31517149, 2019). "It shares some common features with autosomal dominant tubulointerstitial kidney diseases caused by mutations in MUC1 (mucin 1, 1q21), HNF1B (HNF1beta, 17q12), REN (renin, 1q32) and SEC61A1 (Sec 61 translocon alpha 1 subunit, 3q21)." (PMID 28437467, 2017). "Heterozygous mutations in the genes encoding uromodulin (UMOD), hepatocyte nuclear factor 1β (HNF1B), renin (REN) and mucin-1 (MUC1) can result in autosomal dominant tubulointerstitial kidney disease (ADTKD)." (PMID 28701203, 2017).
hyperuricemia (16 papers, 2018 to 2026). An abnormally high level of uric acid. "In her laboratory results, there was hyperuricemia, hyperlipidemia, and hypomagnesemia, also probably related to the HNF1B mutation." (PMID 37511676, 2023). "Despite this, the authors concluded that gout and hyperuricemia are general features of HNF1B mutations." (PMID 34362049, 2021). "Hyperuricemia is a key hallmark of the disease that has been repeatedly reported in patients with HNF1B mutation." (PMID 34362049, 2021). "Although the authors claimed hyperuricemia is a feature of HNF1B mutation, the conclusions are vague due to the small sample size." (PMID 34362049, 2021). "Electrolyte imbalances, including hypomagnesemia, hyperuricemia, and hypokalemia, are also common in patients with HNF1B mutations, as shown in our study." (PMID 32708349, 2020). "Electrolyte imbalances, such as hypomagnesemia, hypokalemia, and hyperuricemia, are also a common feature of HNF1B mutations." (PMID 32708349, 2020). "We aimed to assess a causal relationship between elevated sUA level and HNF1B defects by comparing patients with and without mutations, and to investigate the predictive value of hyperuricemia for distinguishing HNF1B mutation carriers among patients with a range of renal anomalies." (PMID 34362049, 2021). "Extrarenal features of HNF1B mutations include early-onset diabetes mellitus, pancreatic hypoplasia, developmental delay, genital tract malformations, abnormal liver function, hypomagnesemia, hyperuricemia, and early-onset gout." (PMID 32164334, 2020). "Importantly, in our study hyperuricemia was present in 42.5% of HNF1B mutation carriers." (PMID 34362049, 2021). "Tubulointerstitial lesions are the predominant feature of HNF1B-related renal disease, with hyperuricemia showing limited predictive value despite its common occurrence." (PMID 41924323, 2026). "Nevertheless, hyperuricemia and hyperparathyroidism are poor predictors of HNF1β defects as it is also common in other forms of end-stage renal disease." (PMID 35554666, 2022). "We show that hyperuricemia is a relatively common feature in patients with HNF1B-related kidney disease, already present in early childhood." (PMID 34362049, 2021). "Many patients have hyperuricaemia and some present early gout flare, based on regulation of transcription of the uromodulin (umod) gene by HNF1B, which is involved in urate transport." (PMID 32864159, 2020). "Still, it is unclear whether hyperuricemia is an initial feature of HNF1B-related chronic kidney disease or an independent feature." (PMID 37511676, 2023). "Although this association is described in many studies, when compared to patients without HNF1B mutation, the frequency of hyperuricemia in patients with HNF1B mutation was not significantly different." (PMID 34362049, 2021). "Mean sUA was higher and hyperuricemia more prevalent (42.5% vs. 15.4%) in HNF1B carriers." (PMID 34362049, 2021). "Importantly, the frequency of hyperuricemia was compared to that present in counterparts who are negative for HNF1B mutations." (PMID 34362049, 2021). "Thus, we hypothesized that hyperuricemia might be misdiagnosed and under-recognized, especially in children, and this could limit investigations aimed at assessing its usefulness as a predictor of HNF1B disease." (PMID 34362049, 2021). "In other studies, the frequency of hyperuricemia was not significantly different compared to HNF1B negative patients." (PMID 34362049, 2021). "As we showed, the utility of hyperuricemia as a predictor of HNF1B-related disease is limited, and should not be relied upon when selecting patients for genetic testing." (PMID 34362049, 2021). "Indeed, the screening tool to select patients eligible for genetic analysis of the HNF1B gene (HNF1B score) does not recognize hyperuricemia as a weighted parameter." (PMID 34362049, 2021).
hyperuricemia (continued). "In this respect, we provide the evidence that hyperuricemia is not an accurate predictor and, consequently, its application in HNF1B score might be of little value." (PMID 34362049, 2021).
chronic kidney disease (15 papers, 2018 to 2025). Impairment of the renal function secondary to chronic kidney damage persisting for three or more months. "Renal management is a particularly critical aspect of treatment in patients carrying HNF1B variants, as these individuals will develop renal dysfunction by the age of 45 years, and half will progress to end-stage renal disease." (PMID 40901483, 2025). "The diverse spectrum of manifestations associated with HNF1B-related renal disease often leads to diagnostic delays, contributing to significant progression in chronic kidney disease and increased disease burden." (PMID 38674137, 2024). "Variants in the HNF1B gene are the most frequent cause of monogenic congenital anomalies of the kidney and urinary tract and remain one of the major causes of chronic kidney disease (CKD) in the prenatal and childhood period." (PMID 36793123, 2023). "A recent multicentre retrospective cohort study of patients with HNF1β mutations showed that stage 3–4 chronic kidney disease was present in 44% of cases, and end-stage renal disease in 21% of cases." (PMID 29764441, 2018). "In particular, patients with HNF1B deficiency typically presented renal hypoplasia and agenesia, familial juvenile hyperuricemic nephropathy, glomerulocystic kidney disease, and renal interstitial fibrosis, eventually leading to chronic kidney disease." (PMID 36672242, 2023). "Similarly, we described a case of HNF1B deficiency affected by chronic renal disease due to multicystic kidney involvement, bilateral cryptorchidism, and autism spectrum disorder." (PMID 36672242, 2023). "It remains unclear whether raised sUA is a feature of HNF1B-related disease and is directly related to mutation, or if this symptom is a byproduct of chronic kidney disease (CKD), which could be present during the course of the disease." (PMID 34362049, 2021). "Of note, chronic kidney disease may contribute to elevated PTH levels on top of direct HNF1β effects." (PMID 35554666, 2022).
breast carcinoma (14 papers, 2009 to 2023). "Early‐stage breast cancer samples exhibited 73% methylation patterns establishing the role of HNF1B methylation with epigenetic reprogramming and carcinogenesis in breast tumours, confirming the role of the epigenome in carcinogenesis." (PMID 33580750, 2021). "Additional studies in breast cancer have also emphasized HNF1B overexpression in inducing EMT in epithelial NMuMG cells." (PMID 33580750, 2021). "A previous study had reported that some homeobox genes, such as HOXB13, TLX1, and HNF1B, were hypermethylated in the early stages of breast cancer." (PMID 32156290, 2020). "Epigenetic silencing of the HNF1B gene has also been reported in some human cancers, including colorectal carcinoma, breast cancer, or OC." (PMID 28241454, 2017). "Recent analysis of HNF1B in breast cancer has also indicated HNF1B overexpression induces transformation and epithelial-to-mesenchymal transition in the NMuMG epithelial cell-line, providing further evidence of an oncogenic role of HNF1B in cancers of epithelial origin." (PMID 29156765, 2017). "Whether in HR+ or HR− subtype, HER2-positive breast cancer was characterized by gains in 17q12 (ERBB2, CDK12, HNF1B, RAD51D), and almost no gains of 17q12 were present in the other subtypes." (PMID 37264417, 2023).
colorectal cancer (13 papers, 2006 to 2025). A primary or metastatic malignant neoplasm that affects the colon or rectum. "This is biologically plausible; HNF1B is frequently reduced (and sometimes promoter-methylated) in colorectal carcinomas and low levels associate with recurrence and shorter disease-free survival, indicating a tumor-suppressive role." (PMID 41007818, 2025). "Initially described as a gene causing maturity‐onset diabetes of the young (MODY), HNF1β expression deregulation and single nucleotide polymorphisms in HNF1β have now been associated with several tumours including endometrial, prostate, ovarian, hepatocellular, renal and colorectal cancers." (PMID 33580750, 2021). "Genomic analysis and visualization platforms have established that HNF-1β expression correlates positively with the overall survival rates of colorectal cancer patients." (PMID 39650157, 2024). "A study to understand DNA methylation in colorectal cancer identified HNF1B methylation in colorectal patients." (PMID 33580750, 2021). "Moreover, we described quantitative changes on the level of overall HNF1B mRNA expression and showed a positive correlation between decreased mRNA level and decreased protein level in colorectal cancer." (PMID 34997048, 2022). "Consistently, the protein level of HNF1B is also highest in 786-O ccRCC cell line compared to other cancer cell lines, such as SW620 (colorectal cancer), HeLa (cervical carcinoma), KTC-1 (thyroid cancer), T24 (bladder cancer), A375 (melanoma), H1299 and A549 (non-small cell lung cancer)." (PMID 39915461, 2025).
Hyperglycemia (12 papers, 2019 to 2026). An increased concentration of glucose in the blood. "Birth weight is normal, as long as maternal hyperglycemia is properly treated, but if the fetus carriers HNF1B-deficiency, the birth weight is typically low." (PMID 36672242, 2023). "Fifty percent of patients with MODY5 have a whole gene deletion of HNF1B which is associated with severe pathology, elevated HbA1c, hyperglycemia, and decreased insulin secretion with progressive pancreatic β cell dysfunction." (PMID 36573710, 2022). "We present an unusual case of a prenatal diagnosis that revealed a mutation in the HNF1b gene responsible for neonatal hyperglycemia in a pregnant woman affected by X-linked ectodermal dysplasia." (PMID 33259036, 2021). "The clinical characteristics in those neonatal diabetic patients with HNF1B mutations include hyperglycemia, renal abnormalities and genital malformations (e.g., vaginal and Mullerian aplasia)." (PMID 31441606, 2019). "Heterozygous mutations (e.g., missense mutations, complete gene deletions, little fragment deletions or insertions), half of which are de novo, show autosomal dominant inheritance and cause a clinical spectrum with renal cysts and hyperglycemia, (HNF1B-MODY, MODY5)." (PMID 35052457, 2022). "Evidence that hyperglycemia may be present immediately after birth confirms that in patients carrying HNF1b mutation the glycemic defect is due to neonatal insulin deficiency." (PMID 33259036, 2021). "In HNF1B-MODY hyperglycemia is usually diagnosed in the young adulthood (mean age of 26 with a range of 10–61)." (PMID 35052457, 2022). "Mutation in the HNF1B gene can result in severe non-diabetic renal disease, glomerulocystic kidney disease, and hyperglycemia." (PMID 36573710, 2022).
Obesity (11 papers, 2009 to 2024). Accumulation of substantial excess body fat. "HNF1b is a target of mir-802 in the development of obesity-associated impairment of glucose metabolism." (PMID 32623698, 2021). "Interestingly, when stratified by obesity status, rs7501939 at HNF1B only increased PCa risk in obese AAM (OR = 2.14, 95%CI = 1.2–3.8, P = 0.01) but not in the nonobese AAM (P = 0.76) or EAM of any BMI (P = 0.3 in obese, and P = 0.8 in nonobese EAM)." (PMID 24386569, 2013). "In the liver, Mir802 is induced by obesity and impaired glucose tolerance, and it attenuates insulin sensitivity by downregulation of Hnf1b." (PMID 39589393, 2024).
ciliopathies (10 papers, 2014 to 2023). "Despite the frequent and peculiar involvement of the kidneys and pancreas, HNF1B deficiency has increasingly emerged as a multifaceted syndromic ciliopathy affecting several organs, among which the liver seems to be quite relevant." (PMID 36672242, 2023). "Based on this evidence, HNF1B deficiency is included in the wide spectrum of syndromic ciliopathies with liver involvement." (PMID 36672242, 2023). "In accordance with these findings, it has recently been stated that a ciliopathy like HNF1B deficiency must be regarded as a new condition to be included in the diagnostic work-up of neonatal/infantile cholestasis, when PILBD is observed at liver biopsy and other features of AGS are absent." (PMID 36672242, 2023). "However, mutations in HNF1B or genes that typically cause other ciliopathies, such as nephronophthisis, Bardet Biedl, Joubert syndrome, and related disorders, can mimic ARPKD." (PMID 25114813, 2014). "In 4 of them, the cause of the genetic disease was pathogenic variants related with ciliary function (2 confirmed cases, 2 suspected), such as PMM2 and HNF1B, carrying overlapped phenotypes with ciliopathies." (PMID 35401179, 2022). "These disorders include HNF1B and the diverse group of ciliopathies, such as nephronophthisis, Bardet Biedl, and Joubert syndrome." (PMID 25114813, 2014).
Hypokalemia (9 papers, 2019 to 2025). An abnormally decreased potassium concentration in the blood. "Nevertheless, hypokalemia and metabolic alkalosis are only present in a subset of patients with HNF1β defects, which is in line with the phenotype of patients with FXYD2 or ATP1A1 mutations." (PMID 35554666, 2022). "Not surprisingly, hypokalemia was absent in our cohort, yet serum potassium levels were associated with HNF1B mutations." (PMID 38196016, 2024). "We prevously reported hypocalciuria in children with HNF1B mutations, but had not investigated hypokalemia, hypochloremia, or alkalosis, although hypokalemia has previously been reported in adult patients." (PMID 31517149, 2019). "No subjects had hypokalemia; the mean serum potassium level was lower in the HNF1B cohort." (PMID 38196016, 2024).
Insulin resistance (9 papers, 2010 to 2025). Increased resistance towards insulin, that is, diminished effectiveness of insulin in reducing blood glucose levels. "Patients with HNF1B heterozygous mutations commonly exhibit pancreatic hypoplasia, β-cell dysfunction and insulin resistance." (PMID 34295307, 2021). "Among them, Pparg and Akt2 (targets of mir-30b), Hnf1b, Hnf4a, and Lmna (targets of mir-30d), are well-known genes implicated in T2D or insulin resistance." (PMID 21124896, 2010). "These three individuals had HNF1A, HNF1B, and GCK variants, respectively, and they exhibited phenotypes associated with insulin resistance, including high BMI, hypertension, dyslipidaemia, and elevated fasting C‐peptide levels." (PMID 40966384, 2025). "The more specific phenotypes of MIDD, HNF1B and insulin resistance mean single gene/specific insulin resistance panel testing may still be appropriate for these clinical presentations." (PMID 37033247, 2023). "In addition, the HNF1β knockdown also stimulated insulin resistance in hepatocytes, which was also ameliorated by NAC." (PMID 37371492, 2023). "miR-802 is highly expressed in the liver and pancreas, and regulates insulin resistance by targeting HNF1 homeobox B (HNF1B) in the liver, while its function in the pancreas remains unknown." (PMID 28747214, 2017). "The MODY probability score is not suitable for those requiring cascade testing or those with a syndromic phenotype such as those consistent with HNF1B, MIDD, or a severe insulin resistance phenotype." (PMID 37033247, 2023).